CDKN1B (cyclin dependent kinase inhibitor 1B)
Diseases named in the same sentence as CDKN1B in open-access papers (continued):
Sharing a sentence is not in itself a finding about the gene and the disease.
non-small cell lung carcinoma (9 papers, 2013 to 2024). A group of at least three distinct histological types of lung cancer, including non-small cell squamous cell carcinoma, adenocarcinoma, and large cell carcinoma. "The combination of metformin and pemetrexed exhibited an antiproliferative effect by affecting the cell cycle in non-small-cell lung cancer via downregulation of CCNA2 and CCND1, and the upregulation of CDKN1B." (PMID 35480884, 2022).
breast tumor (8 papers, 2010 to 2024). "In both cell lines and primary patient samples, we observed consistent expression patterns of these biomarkers varies by cancer indication, such that ERBB3 and CDKN1B expression are relatively high in breast tumors while EGFR expression is relatively high in other indications." (PMID 27035903, 2016). "Thus, if cell lines are representative of the derivative disease, one would expect to see higher levels of EGFR and lower levels of ERBB3 and CDKN1B in non-breast indications vs. breast tumors." (PMID 27035903, 2016).
diabetes (8 papers, 2008 to 2024). "Conversely, the deletion of p27Kip1 (Cdkn1b−/−) increases the proliferation of β-cells under normal circumstances, as well as in genetic models of insulin resistance and diabetes (Irs2−/− or db/db), the latter of which exhibits an improvement in glucose homeostasis." (PMID 35563231, 2022).
metastatic tumors (7 papers, 2010 to 2023). "Again, mutation of CDKN1B in metastatic tumors was restricted to some specific cancer types, including PC and BC." (PMID 30065701, 2018). "Strengthening this result, the opposite alterations, CDKN1B deletions (0.2% in metastases vs. 0.1% in local disease, p = 0.09) and mutations (1.9% in metastases vs. 1.1% in local disease, p = 0.05), trend toward significant enrichment in metastatic tumors." (PMID 32374727, 2020). "In GB-S9, amplification of cell cycle-related oncogenes CDKN1B and CCNE1 was uniformly observed from primary GBAC to regional and distant metastatic tumors." (PMID 36476508, 2022). "One possible interpretation of our data is that CDKN1B amplification in primary tumors acts to slow the rate of tumor proliferation and metastasis, which would point toward the possible utility of CDK4/6 inhibitors as a means of delaying progression to metastatic disease." (PMID 32374727, 2020).
multiple myeloma (7 papers, 2010 to 2025). "In this context, 2 key myeloma markers, MYC and DKK1, as well as many other cancer-associated genes, including ADM, HDGF, IL15, HGF, STMN1, CDKN1B and CD82, were potentially regulated by the predicted ligands." (PMID 41056512, 2025). "Aberrant downregulating CDKN1B may promote the proliferation of multiple myeloma cells." (PMID 28384236, 2017).
pancreatic NET (7 papers, 2016 to 2025). "Pancreatic NETs have variations in DAXX, ATRX, PTEN, and TSC2, whereas GI-NETs have identified CDKN1B and RASSF1A as the recurrent mutations." (PMID 29255447, 2017). "CDKN1B mutation was found in five cases of small intestinal NET, whereas MEN1 mutation was found in five cases of pancreatic NET." (PMID 26684240, 2016). "Pancreatic NETs have been illustrated to carry somatic mutations in MEN1, DAXX, ATRX, PTEN, and members of the mTOR signaling pathway, whereas gastrointestinal NETs have been reported to harbor CDKN1B mutations." (PMID 37047300, 2023). "Pancreatic NETs frequently exhibit changes in genes such as MEN1, DAXX, ATRX, TSC1, TSC2, CDKN1A, and CDKN1B, along with alterations in CDKN2A and SETD2 in metastatic lesions." (PMID 41426335, 2025).
pheochromocytoma (7 papers, 2008 to 2022). "Here, we describe that the rat MENX line, carrying a Cdkn1b (p27) frameshift-mutation, spontaneously develops pseudohypoxic pheochromocytoma (p-PCC)." (PMID 33401758, 2021). "MENX rats represent a third rodent model of pheochromocytoma; these rats possess homozygous frameshift mutations in CDKN1B and develop tumors of the adrenal medulla alongside other endocrine tumors." (PMID 26793165, 2015). "Recent studies have also highlighted the predisposition of Cdkn1b-mutated rats in developing pheochromocytoma, although no cases have been reported in humans yet." (PMID 35355569, 2022).
corticotropinomas (6 papers, 2016 to 2022). "However, the nuclear CDKN1B (P27) staining was particularly affected, compared with other corticotropinomas." (PMID 28533356, 2017).
endometrial cancer (6 papers, 2010 to 2024). Primary or metastatic malignant neoplasm involving the endometrium (mucous membrane that lines the endometrial cavity). "Our data thus suggest that these correlations between SESN2 and cell cycle-associated genes are independent of the role of CDKN1A and CDKN1B as tumor suppressors in the tumor of patients with endometrial cancer." (PMID 32899752, 2020).
familial isolated hyperparathyroidism (6 papers, 2017 to 2025). A rare, autosomal dominant hereditary syndrome characterized by hypercalcemia, abnormally high levels of parathyroid hormone, and isolated hyperfunctioning parathyroid tumors. "Non-syndromic hereditary hyperparathyroidism, called familial isolated hyperparathyroidism (FIHP), can be caused by the incomplete manifestation of mutations of syndrome-related genes such as MEN-1, CDC73, GCM2, CDKN1A, CDKN1B, or CDKN2C." (PMID 36900197, 2023).
lymph node metastasis (6 papers, 2006 to 2024). "Low expression of CDKN1B in tumor tissues was associated with higher Gleason score, T stage, and lymph node metastasis in patients." (PMID 38997648, 2024).
small intestinal NETs (6 papers, 2016 to 2025). "Small-intestinal NETs also have a very low mutational rate, with the only recurrent mutations occurring in the CDKN1B gene in 8% of cases and loss of chromosome 18 observed in 50%–80% cases." (PMID 40026252, 2025).
acute myeloid leukemia (5 papers, 2014 to 2023). Acute myeloid leukemia (AML) is a group of neoplasms arising from precursor cells committed to the myeloid cell-line differentiation. "In addition, CDKN1B expression can be a useful prognostic molecular marker for acute myeloid leukemia, where low CDKN1B expression is associated with high proliferation and, therefore, with a favorable response to chemotherapy." (PMID 27366593, 2015). "Recently, a cell-line based experiment indicates that knockdown of PIP4K2A in acute myeloid leukemia (AML) results in accumulation of the cyclin-dependent kinase inhibitors (i.e., CDKN1A and CDKN1B), G1 cell cycle arrest and apoptosis." (PMID 30697230, 2018).
cholangiocarcinoma (5 papers, 2017 to 2025). A carcinoma that arises from the intrahepatic biliary tree (intrahepatic cholangiocarcinoma) or from the junction, or adjacent to the junction, of the right and left hepatic ducts (hilar cholangiocarcinoma). "Similarly, NUP358 regulates cyclin-dependent kinase inhibitor 1 B (CDKN1B) nuclear-cytoplasmic translocation by promoting CDKN1B SUMOylation at K73, thereby facilitating cholangiocarcinoma cell proliferation." (PMID 39080077, 2024).
renal carcinoma (5 papers, 2004 to 2024). A carcinoma arising from the epithelium of the renal parenchyma or the renal pelvis. "A study performed on human renal cancer cell line treated with metformin, indicated that metformin may induce cell cycle arrest by up-regulating the level of miR-34a, decreasing the level of cyclin D1 expression and enhancing cyclin-dependent kinase inhibitor 1B (p27Kip1) expression." (PMID 33849540, 2021).
chronic lymphocytic leukemia (4 papers, 2014 to 2025). "In people CDKN1B, encoding for p27Kip1, has been identified as the second most common altered gene by frame-shift mutations in heterozygosity in hairy cell leukemia (HCL), a form of B-cell CLL." (PMID 36033505, 2022).
chronic myeloid leukemia (4 papers, 2013 to 2026). "Moreover, bosutinib, a tyrosine kinase inhibitor, is perhaps the best candidate identified, as it is already in use against chronic myeloid leukemia and was found to target five upregulated proteins (CDC37, CDKN1B, GRB2, RASSF1, and SMAD2)." (PMID 39202022, 2024).
colorectal tumors (4 papers, 2006 to 2022). "Accordingly, we observed an increase of Cdkn1b and Cdkn1c gene expression only in the ubiqDll4-/- small and large intestinal tumors relatively to the controls and to the endoDll4-/- mice." (PMID 28086833, 2017). "Colorectal tumours with high levels of CKS1 and SKP2 generally exhibit a more aggressive behaviour and are associated with low levels of CDKN1B (p27) and loss of tumor differentiation." (PMID 16919171, 2006).
endometriosis (4 papers, 2020 to 2024). The growth of functional endometrial tissue in anatomic sites outside the uterine body. "Endometriosis has been associated with decreased expression of cyclin-dependent kinase inhibitor 1B (p27Kip1) in epithelial and stromal cells of endometrium." (PMID 34068967, 2021). "Moreover, p27kip1 (Cyclin-Dependent Kinase 1B inhibitor, CDKN1B) could also be significant within the framework of endometriosis." (PMID 38398227, 2024).
hairy cell leukemia (4 papers, 2020 to 2025). Hairy cell leukemia (HCL) is a rare type of leukemia in which abnormal B-lymphocytes are present in the bone marrow, spleen and peripheral blood. "CDKN1B was also identified as the second most common mutated gene in hairy cell leukemia, suggesting that CDNK1B may act as a novel cancer suppressor gene." (PMID 32590883, 2020). "Among other deregulated genes were cyclin kinase inhibitors CDKN1B (p27kip1) and CDKN2C (p18/INK4AC), mutations of the former being found in hairy cell leukemias." (PMID 34017329, 2021).
Hypertension (4 papers, 2008 to 2024). The presence of chronic increased pressure in the systemic arterial system. "Existing studies have shown that NETs promote the proliferation of vascular smooth muscle cells through the Hippo-YAP pathway and Akt/CDKN1b/TK1 pathway in abdominal aortic aneurysm and hypertension, respectively." (PMID 38664728, 2024).
intrahepatic cholangiocarcinoma (4 papers, 2014 to 2025). A carcinoma that arises from the intrahepatic bile duct epithelium in any site of the intrahepatic biliary tree. "Furthermore, YTHDF2 increased CDKN1B mRNA degradation in an m6A-dependent manner, which promoted intrahepatic cholangiocarcinoma (ICC) progression and reduced sensitivity to cisplatin treatment." (PMID 36517820, 2022). "YTHDF2 facilitates cyclin-dependent kinase inhibitor 1B (CDKN1B) mRNA degradation and plays a cisplatin-desensitizing role in intrahepatic cholangiocarcinoma (ICC)." (PMID 40483535, 2025).
mesothelioma (4 papers, 2003 to 2021). A usually malignant and aggressive neoplasm of the mesothelium which is often associated with exposure to asbestos. "With this background, CDKN1B could also be explored as a putative resistance marker in mesothelioma." (PMID 22905093, 2012).
Obesity (4 papers, 2015 to 2024). Accumulation of substantial excess body fat. "Thus, upregulation of miR-222-3p may cause Cdkn1b: miR-222-3p mediated apoptosis in VAT in obesity." (PMID 29507687, 2018). "CDKN1B was shown to be a potential predictor of advanced hyperinsulinemia, but this gene might be novel target for obesity." (PMID 34248836, 2021).
renal cell carcinoma (4 papers, 2008 to 2023). "Expression of CDKN1B is significantly decreased in renal cell carcinoma (RCC) as compared with normal kidney tissue." (PMID 24605326, 2014).
viral infection (4 papers, 2012 to 2025). "We found that molecules like SOX2, FGFR3, and CDKN1B could be more affected by different viruses than other molecules shaping the auditory system, suggesting that cochlear development and production of hair and supporting cells might be disrupted by certain viral infections during embryogenesis." (PMID 33419104, 2021).
adrenal adenoma (3 papers, 2022 to 2025). "MEN4, associated with CDKN1B mutations, similarly predisposes to endocrine and non-endocrine tumors, including adrenal adenomas and rare cortisol-secreting lesions." (PMID 41007858, 2025).
carcinoma in situ (3 papers, 2010 to 2023). "CDKN1B nuclear expression was clearly reduced in an in situ carcinoma and almost absent in an adenocarcinoma from Men1+/- mice." (PMID 20663219, 2010).
gastrinomas (3 papers, 2019 to 2023). "Of note, cases of NF-panNENs and gastrinomas have been described in the setting of multiple neuroendocrine neoplasia type 4, a recently described syndrome due to the mutation of the CDKN1B gene." (PMID 34885063, 2021).
heart failure (3 papers, 2020 to 2024). Inability of the heart to pump blood at an adequate rate to meet tissue metabolic requirements. "Some C/EBPβ target genes, for example, OSMR, MAP2K3 and CDKN1B also have been studied in heart failure developmental progress." (PMID 32460775, 2020).
Hyperinsulinemia (3 papers, 2016 to 2025). An increased concentration of insulin in the blood. "In fact, key metabolic features of T2D, such as hyperinsulinemia, chronic low‐grade inflammation, and impaired glucose homeostasis, may modulate the functional effects of CDKN1B and TCF7L2 variants." (PMID 40658092, 2025).
influenza infection (3 papers, 2014 to 2025). "In depth assays further uncovered the role of cyclin-dependent kinase inhibitor 1B (Cdkn1b) in influenza infection by using p27-/- mice." (PMID 24952721, 2014). "The analysis revealed that the core targets of Chicoric acid against influenza are UBA52, UBC, HCK, CDKN1B, and RPS27A." (PMID 41303371, 2025). "We quantified the expression of four human mRNAs, two mRNAs that are significantly reduced during influenza infection (CHML and KIF18A, cluster 1) and two mRNAs that were less affected by infection (MYC and CDKN1B, cluster 3)." (PMID 27525483, 2016).
myeloid leukemia (3 papers, 2017 to 2020). A clonal proliferation of myeloid cells and their precursors in the bone marrow, peripheral blood, and spleen. "Previous results in our laboratory in a human myeloid leukemia cell line K562 have shown that Myc ́s ability to promote cell cycle progression depends on the reduction of p27 (p27KIP1, CDKN1B) protein levels." (PMID 31822694, 2019).
renal angiomyolipoma (3 papers, 2012 to 2015). "A germline nonsense mutation in the human CDKN1B gene, encoding p27 protein, a negative regulator of cell cycle progression, has indeed been identified in a MEN 1 proband with acromegaly and PHPT, and a first-degree relative carrier with renal angiomyolipoma." (PMID 23209466, 2012).
retinoblastoma (3 papers, 2011 to 2023). A malignant tumor that originates in the nuclear layer of the retina. "Besides its effect on growth factors, Tig1 overexpression also promotes the downregulation of genes encoding factors that promote cell cycle progression, and the upregulation of genes encoding the tumour suppressors Cdkn1B and Retinoblastoma, consistent with the anti-proliferative effect of Tig1." (PMID 35241664, 2022).
somatotropinoma (3 papers, 2019 to 2025). "While somatic mutations of GNAS are the most prevalent cause of somatotroph tumors, germline mutations in various genes (AIP, PRKAR1A, GPR101, GNAS, MEN1, CDKN1B, SDHx, MAX) are also known as the cause of somatotroph tumors." (PMID 36010855, 2022).
T-cell lymphomas (3 papers, 2011 to 2017). "In anaplastic large cell lymphoma (ALCL), an aggressive human T cell lymphoma, miR-106a~363 is highly expressed (especially miR-106a and miR-20b), whereas the same tumor type typically exhibits a PI3K-dependent loss of the Cdk inhibitor protein p27Kip1 (Cdkn1b)." (PMID 28881594, 2017).
triple-negative breast carcinoma (3 papers, 2020 to 2022). An invasive breast carcinoma which is negative for expression of estrogen receptor (ER), progesterone receptor (PR), and human epidermal growth factor receptor 2 (HER2). "High expressed miR-455-5p may exert tumor promoting roles by inhibiting the expression of CDKN1B and influencing cell cycle, which led to poor prognosis in basal-like subtype (i.e. triple-negative breast cancer, TNBC)." (PMID 31763681, 2020).
cardiac hypertrophy (2 papers, 2016 to 2022). "miR-221 is thought to play a role in the development of cardiac hypertrophy in heart disease via targeting of cyclin-dependent kinase inhibitor 1B (p27)." (PMID 27213331, 2016).
COVID-19 (2 papers, 2022 to 2024). A disease caused by infection with severe acute respiratory syndrome coronavirus 2. "We found here that CDKN1B gen is a shared target of miR-146a, miR-221-3p, and miR-155-5p, paving the way for therapeutic interventions in severe COVID-19 patients." (PMID 36611425, 2022).
cyst (2 papers, 2022). A sac-like closed membranous structure that may be empty or contain fluid or amorphous material. "While CDKN1B and CDKN1C expression was higher in normal subtypes, senescence-related CDK inhibitors CDKN1A and CDKN2A were more abundant in PKD-CDC subtypes, suggesting that cyst-lining cells may be prone to cellular senescence due to cellular stress." (PMID 36310237, 2022).
developmental delay (2 papers, 2013 to 2019). "Further studies are warranted to delineate how commonly CDKN1B mutations are involved in developmental delay and whether all these cases are similar to the result of reduced CDKN1B protein expression." (PMID 23505216, 2013). "We propose a recessive model where decreased dosage of CDKN1B during development in humans results in a neuronal phenotype akin to that described in mice, placing CDKN1B as a candidate gene involved in developmental delay." (PMID 23505216, 2013).
endocrine tumors (2 papers, 2015 to 2025). "This case highlights the coexistence of MTC and MEN4 linked to a novel CDKN1B germline frameshift mutation, expanding the understanding of MEN4-associated endocrine tumors." (PMID 40507982, 2025).
esophageal squamous cell carcinoma (2 papers, 2014). Esophageal squamous cell carcinoma (ESCC) is a type of esophageal carcinoma (EC) that can affect any part of the esophagus, but is usually located in the upper or middle third. "SMAD4 is enriched in adherens junction and cell cycle pathways and has been found to have a potential predictive value for esophageal squamous cell carcinoma in patients receiving neoadjuvant chemoradiotherapy RBL2 and CDKN1B are enhanced in cell cycle pathways." (PMID 24604236, 2014).
germ cell tumor (2 papers, 2023). A benign or malignant, gonadal or extragonadal neoplasm that originates from germ cells. "The most prevalent changes in germ cell tumors are CDKN1B Amplification, KRAS Amplification, CCND2 Amplification, ETV6 Amplification, and RAD52 Amplification." (PMID 37958970, 2023). "KRAS, CDKN1B, CCND2, ETV6, and RAD52 mutations are the most common in germ cell tumors." (PMID 37958970, 2023).
hepatitis B (2 papers, 2020 to 2021). "It has also been shown that miR-125b is associated with hepatitis B and has been targeted with genes that include IL6, DDX3X, STAT2, STAT3, SMAD4, CDKN1B, MAP3K1 and so on from our results." (PMID 34988221, 2021).
leiomyoma (2 papers, 2007 to 2019). A well-circumscribed benign smooth muscle neoplasm characterized by the presence of spindle cells with cigar-shaped nuclei, interlacing fascicles, and a whorled pattern. "The results of differential expression of hallmark genes after miR-150 mimic transfection and in silico analysis suggested that p27Kip1 (or CDKN1B) is one of the target genes of miR-150 in leiomyoma." (PMID 31159158, 2019).
prostate tumors (2 papers, 2010 to 2019).